RNU4-76P (RNA, U4 small nuclear 76, pseudogene)
Gene: Small nuclear RNA gene on chromosome 6 (121,542,486 to 121,542,626, reverse strand). Ensembl gene ENSG00000201379.
Homologues: Orthologues: chimpanzee U4 (100% identical). Paralogues in human: RNU4-13P (85% identical), RNU4-68P (84% identical), RNU4-7P (84% identical), RNU4-23P (84% identical), RNU4-44P (83% identical), RNU4-67P (83% identical), RNU4-42P (82% identical), RNU4-58P (82% identical), RNU4-84P (82% identical), RNU4-35P (82% identical), RNU4-8P (81% identical), RNU4-45P (80% identical), and 81 more.